MTHFD2 (methylenetetrahydrofolate dehydrogenase (NADP+ dependent) 2, methenyltetrahydrofolate cyclohydrolase)
Diseases named in the same sentence as MTHFD2 in open-access papers (continued):
Sharing a sentence is not in itself a finding about the gene and the disease.
cancer (continued). "We show that the human FolD orthologs, MTHFD1 and MTHFD2, are also inhibited in the low nM range, and that micromolar concentrations of carolacton inhibit the growth of cancer cell lines." (PMID 29142318, 2017). "Knockdown of MTHFD2 decreases proliferation of cancer cell lines and downregulates their migration and invasion." (PMID 28177894, 2017). "Mitochondrial enzymes SHMT2 and MTHFD2 are the key components of the folate cycle and their deregulation plays a pivotal role in the cancer-related one-carbon metabolism." (PMID 28177894, 2017). "Mthfd2 has been identified in a screen of 19 cancer cell types as one of the 50 most commonly overexpressed genes." (PMID 29225823, 2017). "Understanding how MTHFD2 is involved in both of these biological processes is of critical importance to effectively develop therapeutics targeting this enzyme for cancer treatment." (PMID 29225823, 2017). "MTHFD2 is expressed mostly in embryonic and cancer tissues, whereas in the mitochondria of normal adult tissues, MTHFD2 activity is carried out by the product of a different gene, MTHFD2L." (PMID 27635066, 2016). "MTHFD2 RNA and protein are markedly elevated in many cancers and negatively correlated with survival in breast cancer." (PMID 27767057, 2016). "Folate Metabolism: Folate metabolism, in particular the enzyme methylenetetrahydrofolate dehydrogenase (MTHFD2), has been shown to be up-regulated in cancer cells, and it has been shown to contribute to energy and purine requirements in cancer." (PMID 26942765, 2016). "Although the enzymatic activity of the MTHFD2 protein is well understood, little is known about its larger role in cancer cell biology." (PMID 26461067, 2015). "The enzyme MTHFD2 in this pathway is highly expressed in human tumors and broadly required for survival of cancer cells." (PMID 26461067, 2015). "In many cancer cells MTHFD2 is localized in mitochondrial, however its localization in adult cardiomyocytes of TazKD mice is unclear." (PMID 26030409, 2015). "Taken together, these results demonstrate that the MTHFD2 enzyme is present in both the mitochondria and the nucleus of cancer cells." (PMID 26461067, 2015). "Within the mitochondrial folate pathway, the MTHFD2 enzyme is of special interest in cancer research for several reasons." (PMID 26461067, 2015). "Application of [2H]-labeled serine, glycine, and glucose tracers to non-small cell lung cancer cells indicated that serine flux through SHMT2 and MTHFD2(L) operates primarily in the oxidative direction to produce mitochondrial NAD(P)H in these cancer cells." (PMID 25621173, 2015). "This study identifies WIPF2, EPHB4 and MTHFD2 as novel regulators of vimentin expression by using a high-throughput RNAi screening approach targeting cancer relevant genes." (PMID 23295955, 2013). "Despite the initial emphasis on MTHFD2 as a gene induced in cancers, all the way back to the Mejia and MacKenzie 1985 article, the targeting of this enzyme could hold as much or even greater potential as an immunomodulatory strategy." (PMID 41303507, 2025). "Another possibility is that, besides increased cytosolic flux, cancer cells could also utilize enhanced MTHFD2L activity to compensate for the inhibition of MTHFD2." (PMID 41303507, 2025). "Thus, beyond the blockage of cancer-enriched MTHFD2, this drug will also inhibit the essential MTHFD1." (PMID 41303507, 2025). "During embryonic development, MTHFD2 supports rapid proliferation of cells through enzymatic reactions, and MTHFD2 is lowly or not expressed in most adult tissues, whereas in tumors, MTHFD2 is reactivated and highly expressed in a variety of cancers." (PMID 40280919, 2025). "In addition, MTHFD2, a mitochondrial one-carbon metabolism enzyme, is consistently upregulated across cancers and functionally required in AML." (PMID 41295305, 2025). "This raises the possibility that MTHFD2 induction in cancer cells could also be beneficial to cancer cells through its effect on DNA repair." (PMID 41303507, 2025).
cancer (continued). "SHMT2 and MTHFD2 are among the most consistently upregulated metabolic genes in cancer, supporting the critical role of one-carbon metabolism in the production of metabolites to fuel rapid growth and cell division and to survive intra- and extracellular oxidative stress." (PMID 40698729, 2025). "Therefore, as more knowledge relating to MTHFD2 has accumulated, more questions regarding its potential as a cancer drug target and the optimal strategies to use towards this goal have arisen." (PMID 41303507, 2025). "Discrepancies between studies regarding the ability of cancer cells to rapidly metabolically compensate for targeting MTHFD2 could be due to methodological differences." (PMID 41303507, 2025). "Bonagas and colleagues showed that MTHFD2 prevents replication stress in cancer because MTHFD2 downregulation led to thymidine depletion, which resulted in uracil misincorporation with the subsequent DNA damage at replication forks and impairment of DNA duplication." (PMID 40604332, 2024). "A myriad of studies highlight the contribution of MTHFD2 in driving cancer progression." (PMID 40604332, 2024). "Similarly, both isoenzymes are expressed in cancer cells, although MTHFD2 is highly upregulated in a wide range of tumors, in contrast to MTHFD2L." (PMID 40604332, 2024). "This suggests that the apoptotic effect of MTHFD2 inhibition is specific to cancer cells." (PMID 39668825, 2024). "The bifunctional folate enzyme methylene tetrahydrofolate dehydrogenase/cyclohydrolase 2 (MTHFD2) is widely overexpressed in cancer, possesses a highly cancer‐specific expression profile, and has been validated extensively as a promising anticancer target in various tumor types." (PMID 38533616, 2024). "Because MTHFD2 is upregulated and drives cancer progression in a wide variety of tumors, and its expression is low in proliferative and differentiated adult tissues, this enzyme has become very attractive for the development of novel, metabolically-targeted cancer therapies." (PMID 40604332, 2024). "Finally, among the mitochondrial one-carbon folate enzymes, MTHFD2 was particularly responsive to mitogenic stimuli in several cancer cells, and its expression was repressed by growth signal withdrawal and rapidly reinduced upon restimulation." (PMID 40604332, 2024). "Thus, SHMT2 and MTHFD2 are potential targets for cancer treatment due to their specific expression and prognostic value, which attract considerable attention." (PMID 38279895, 2024). "The recent evidence linking the MTHFD2 nuclear pool and its “moonlighting” functions in DNA replication, RNA metabolism, methylation and DNA damage repair to tumorigenesis render this enzyme an intriguing cancer target." (PMID 40604332, 2024). "For this reason, it is hypothesized that MTHFD2 hyperregulation contributes to cancer progression, which is related to aggressive clinicopathological parameters, metastasis, and shorter survival." (PMID 38422037, 2024). "In conclusion, we identify a key role for MTHFD2 in HR repair and describe an interdependency between MTHFD2 and HR proficiency that could potentially be exploited for cancer therapy." (PMID 38533616, 2024). "Thus, MTHFD2-overpexpressing cancers can be targeted by developing potent MTHFD2 inhibitors which presents a new promising therapeutic strategy with minimal side effects." (PMID 39256448, 2024). "In addition, MTHFD2 is known to promote cancer cell proliferation and survival in vitro and support tumor growth in vivo across multiple cancer types." (PMID 40604332, 2024). "Given that SHMT2 and MTHFD2 are overexpressed in cancer, mitochondrial 1C metabolism inhibitors might be more selective than cytosolic antifolates like methotrexate." (PMID 38431691, 2024). "Additionally, MTHFD2 is found to play a role in RNA metabolism and translation by interacting with nuclear proteins in cancer cells." (PMID 38794278, 2024). "RNA interference targeting MTHFD2 can lead to cancer cell death." (PMID 39588377, 2024).
cancer (continued). "Consequently, MTHFD2 was chosen for a more in-depth exploration of its intricate role in aging-related cancer." (PMID 39668825, 2024). "Especially enzymes of the mitochondrial one-carbon metabolism, SHMT2 and MTHFD2 are frequently increased in cancers, however, cancer cells can partly switch to the cytoplasmic isoforms for the generation of methylene-THF and thus the generation of one-carbon units." (PMID 38515202, 2024). "A recent study showed that inhibitors of MTHFD2 lead to the specific death of MTHFD2-expressing cells, suggesting that these therapeutic approaches could be very specific to cancer cells and have minimal impact on normal cells." (PMID 38540202, 2024). "Future research directions for MTHFD2 in the diagnosis and treatment of elderly cancer patients could focus on several key areas." (PMID 39668825, 2024). "Although the involvement of MTHFD2 in cancer cell proliferation is clear, there are a myriad of mechanistic pathways by which MTHFD2 may contribute to carcinogenesis." (PMID 40604332, 2024). "An open question is whether the regulatory signaling mechanisms behind the upregulation of MTHFD2 in cancer are shared during embryonic development or whether these regulatory mechanisms are context specific." (PMID 40604332, 2024). "Taken together, these studies suggest that MTHFD2 is oncogenic and may be an important prognostic indicator as well as a good immunotherapy target in cancers." (PMID 37480214, 2023). "The results reported herein areexpected to benefit medicinal chemists working on the developmentof selective MTHFD2 inhibitors for cancer treatment, although experimentalvalidation by biochemical and/or pharmacokinetic assays is requiredto substantiate the outcomes of the study." (PMID 37125100, 2023). "Therefore, further investigation focusing on the detailed processes of MTHFD2 in regulating cancer immunity is needed in the future." (PMID 38130721, 2023). "In addition to its toxicity in MTHFD2-expressing cancers, we also discover that TH9619 has a potent antitumorigenic effect on cancers deficient in mitochondrial 1C enzymes (MTHFD2 and MTHFD1L) by blocking purine synthesis." (PMID 37012496, 2023). "Moreover, mitochondrial folate enzyme (MTHFD2), as an important immunosuppressive and anticancer agent, is strongly up-regulated in human lymphocytes and cancers." (PMID 36670748, 2023). "Instead, we show that TH9619 targets MTHFD2-expressing cancer cells by inhibiting MTHFD1(DC)." (PMID 37012496, 2023). "The cancer–immunity cycle analysis, which can reflect the immune system regulation step by step, revealed that high MTHFD2 was correlated with higher score of most steps in immune response, including T-cell recruiting, NK cell recruiting, and killing of cancer cells." (PMID 38130721, 2023). "In BLCA, high expression of MTHFD2 was observed to be positively related with the cancer–immunity cycle, the infiltration of several immune cells, and the expression of immunoregulators and T-cell inflamed scores, indicating a positive correlation with the inflamed TME." (PMID 38130721, 2023). "The overexpression of MTHFD2 could provide the basis for biosynthesis of pyrimidine and purine during rapid proliferation of cancer cells which is widely needed for the growth of all tumors." (PMID 37936908, 2023). "Aberrant KRAS activity renders LUAD cancer cell lines vulnerable to MTHFD2 and EZH2 inhibitors." (PMID 37069494, 2023). "The percentage and contribution of CNV to pan-cancer MTHFD2 expression were examined." (PMID 36726381, 2023). "A previous study has indicated that MTHFD2 induced cancer immune evasion." (PMID 37484807, 2023). "On the purine synthesis side, mechanistic target of rapamycin complex 1 (mTORC1) activation induces purine synthesis in both normal and cancer cells by transcriptional control of MTHFD2, which produces 10-formyl THF, the key folate cofactor in purine synthesis." (PMID 37949226, 2023).
cancer (continued). "Specifically, MTHFD2 was positively associated with most immune cells in THCA, PAAD, LIHC, KIRP, KIRC, KICH, and BLCA, whereas it was also negatively associated with most immune cells in some other cancers, such as UCEC, SARC, LUSC, and LUAD." (PMID 38130721, 2023). "In bladder cancer, high expression of MTHFD2 was associated with PD‐L1 activation via the PI3K/AKT signaling pathway, suggesting that it could be a promising marker of cancer immunotherapy." (PMID 37147729, 2023). "Methylenetetrahydrofolate dehydrogenase 2 (MTHFD2) contributes to tumourigenesis and immune evasion in several cancers; however, its biological function in BC remains unknown." (PMID 37480214, 2023). "Moreover, the folate trapping mechanism now provides an incentive for developing MTHFD1(DC)-specific inhibitors to treat MTHFD2-expressing cancers." (PMID 37012496, 2023). "Taken together, these results show that MTHFD2 prevents RS in cancer cells." (PMID 35228749, 2022). "Aberrant SHMT2 and MTHFD2 expression might impair DNA synthesis and damage redox balance, which is important for cancer cell survival." (PMID 36551330, 2022). "To assess the cancer specificity of the replication defects caused by MTHFD2 inhibitors, we treated AML and nontumorigenic LCL cells with TH7299, TH9619, MTX or the ATR inhibitor VE-821." (PMID 35228749, 2022). "MTHFD2 could confer redox homeostasis, promote cancer cell growth metastasis, and correlate with poor survival." (PMID 35693982, 2022). "MTHFD2 has been observed to exert oncogenic effects in a variety of cancers." (PMID 35581573, 2022). "MTHFD2 is one of the key enzymes in 1CM and is strongly expressed in embryonic development but it is almost absent in most healthy adult tissues, making it a promising potential therapeutic target for cancer treatment." (PMID 35888776, 2022). "MTHFD2 also might be a promising novel target for anti-cancer immunotherapy for its strong correlation with immune infiltration." (PMID 35581573, 2022). "Pinning down selectivity: MTHFD2 is an anti‐cancer drug target only expressed in cancer cells." (PMID 35712863, 2022). "In the present study, we perform a comprehensive study to validate MTHFD2 as an anticancer target and develop potent MTHFD2 inhibitors to be used as tools to explore the mechanism of action of MTHFD2 in cancer, as well as to demonstrate their therapeutic potential." (PMID 35228749, 2022). "Interestingly, recent studies have demonstrated that MTHFD2 confers redox homeostasis and drives cancer cell proliferation and migration." (PMID 35135596, 2022). "In the present study, the differential cancer cell cytotoxicity suggests that a synthetic lethality approach may also be possible for MTHFD2 inhibitors, although the detailed genetic context has yet to be established." (PMID 35228749, 2022). "MTHFD2, a mitochondrial one-carbon metabolic enzyme, is dysregulated in several malignancies and may serve as a promising therapeutic candidate in cancer treatment." (PMID 35790743, 2022). "Interestingly, we observed that MCF-7 secretome upregulated MTHFD2, a folate-cycle enzyme shown to induce cancer immune evasion." (PMID 35806196, 2022). "Accordingly, overexpressed MTHFD2 shows a compromised effect in cancer cells with PD-L1 depletion." (PMID 33782411, 2021). "Recent studies show miRNAs can affect cancer progression via manipulating MTHFD2." (PMID 34121323, 2021). "Furthermore, PD-L1 mRNA and protein were decreased in MTHFD2 KD and KO human cancer cells, as well as in mouse embryonic fibroblasts (MEFs)." (PMID 33782411, 2021). "These suggest that, beyond cancer, MTHFD2 may play more roles in immune biology, given the diverse functions of MTHFD2 in cellular activities." (PMID 33782411, 2021). "This suggests that the transcriptional activity of cMYC is suppressed in MTHFD2-KD cancer cells." (PMID 33782411, 2021). "Moreover, MTHFD2 is found to be involved in RNA metabolism and translation by interacting with nuclear proteins in cancer cells." (PMID 34121323, 2021).
cancer (continued). "In general, the results of the bioinformatics analyses implicated that ADAM9, MTHFD2, RRM2, and SLC2A1 are overexpressed in tumors and that the cumulative effect of their overexpression is associated with poor outcomes in multiple types of cancer." (PMID 33664854, 2021). "MTHFD2, a mitochondrial one‐carbon metabolism enzyme, is dysregulated in a variety of cancers." (PMID 34121323, 2021). "Likewise, we have detected notable MTHFD2 mRNA levels in a variety of cancer cell lines, particularly in SW1990 cells." (PMID 33782411, 2021). "Despite its well-known bifunctional dehydrogenase and cyclohydrolase activities, MTHFD2 has been reported to be required for cancer proliferation and may have profound role in tumor development and progression." (PMID 32411609, 2020). "Genetical or pharmacological targeting MTHFD2 is a promising strategy in cancer therapy." (PMID 32411609, 2020). "Downregulating of MTHFD2 could affect cancer cell morphology and possibly impair the ability of migration and invasion." (PMID 32411609, 2020). "Our findings reveal an unknown regulation axis of cisplatin-SIRT3-MTHFD2 in redox homeostasis and suggest a potential therapeutic strategy for cancer treatments by targeting MTHFD2." (PMID 32811824, 2020). "Gene expression profiling could indeed identify many types of MTHFD2-overexpressing tumors and further studies revealed MTHFD2 as an important determinant of cancer cell survival." (PMID 32365833, 2020). "These evidences identify MTHFD2 as a molecular signature for cancer patient stratification." (PMID 32759461, 2020). "Targeting MTHFD2 is thus a promising strategy for anti-cancer therapy." (PMID 32411609, 2020). "Taken together, MTHFD2 is oncogenic in nature and may serve as a prognostic indicator as well as a therapeutic target in cancers." (PMID 32411609, 2020). "It remains unknown whether inhibiting MTHFD2 in these cancers would significantly suppress tumor growth." (PMID 32411609, 2020). "Enforced expression of MTHFD2 was sufficient to promote cancer cell proliferation in serum-deprived condition, indicating that its function might override the growth factor limitation." (PMID 32411609, 2020). "Additionally, gene knockdown studies have revealed the profound impact of MTHFD2 depletion on cancers." (PMID 32411609, 2020). "Because patients with a poor prognosis have a high risk of recurrence after surgery, MTHFD2-targeting therapies could be added to their treatment regimen to prevent recurrence when the expression level of MTHFD2 is high in the resected cancer tissues." (PMID 30532069, 2019). "Taken together, targeting MTHFD2 may attack multiple hallmarks of cancer and likely provide therapeutic benefit." (PMID 30867065, 2019). "Their results provide solid evidence that targeting redox stabilizers, such as MTHFD2, could be a potential therapeutic strategy for treating cancer." (PMID 30867065, 2019). "Moreover, MTHFD2 plays important roles in drug resistance and cancer stem-like properties by depleting the AICAR intracellular pool." (PMID 30532069, 2019). "Thus, MTHFD2-mediated mitochondrial 1C metabolism appears critical for cancer stem-like properties and resistance to drugs including gefitinib through consumption of AICAR, leading to depletion of the intracellular pool of AICAR." (PMID 30532069, 2019). "When cells are dependent on MTHFD2, this enzyme may become rate limiting for the synthesis of sufficient amount of purine nucleotides, promoting rapid growth of cancer cells and CSCs." (PMID 30532069, 2019). "Moreover, overexpression of MTHFD2 alone in gefitinib-sensitive cancer cells conferred gefitinib resistance." (PMID 30532069, 2019). "Understanding this non-enzymatic function is important for optimal targeting of MTHFD2 in cancer." (PMID 30275950, 2018). "Currently, MTHFD2 is tested as a potential drug target for cancer therapy." (PMID 29895827, 2018).